SIRT1 (sirtuin 1)
Diseases named in the same sentence as SIRT1 in open-access papers (continued):
Sharing a sentence is not in itself a finding about the gene and the disease.
colon carcinoma (122 papers, 2006 to 2025). "In conclusion, SIRT1 rs12778366 influenced colon cancer risk in women, which supports that SIRT1, an energy-sensing molecule, is involved in colon cancer development in women." (PMID 30410074, 2018). "Coupled with the observation that SIRT1 expression levels are increased in many human tumors (e.g. colon cancer) and usually associated with poor prognosis in these patients, these findings suggest that SIRT1 acts as a tumor promoter." (PMID 23799088, 2013). "SIRT1 is also expressed in the gut where it exerts anti-inflammatory effects in acute intestinal inflammation and suppresses intestinal tumorigenesis and colon cancer associated with colitis." (PMID 22115311, 2011). "Association between SIRT1 expression and clinicopathological data of patients with colon cancer." (PMID 41020376, 2025). "Notably, human colon cancer (HCT‐116) cells harboring the SIRT1‐S27A mutation showed decreased cell proliferation and reduced capability to form xenograft tumor in athymic nude mice, which was accompanied by diminished transcriptional activity of Snail." (PMID 34826187, 2022). "Colon cancer showed a positive correlation between SIRT1 and CD4+ T cells (r = 0.342), CD8+ T cells (r = 0.25), macrophages (r = 0.253), and neutrophils (r = 0.216), which is promising." (PMID 41020376, 2025). "Sch B also indirectly regulates Smad ubiquitination regulatory factor 2 (SMURF2) by suppressing the protein expression of Sirtuin 1 (SIRT1) and restrains the growth and metastasis of colon cancer cells." (PMID 39995410, 2025). "In breast and ovarian cancers, SIRT1 often correlates with aggressive behavior and therapy resistance, while in colon cancer, its role appears more context-dependent, sometimes contributing to genomic stability under specific conditions." (PMID 41300302, 2025). "Immunohistochemical staining was employed to identify the presence of SIRT1 in gastric cancer (GC), colon cancer (CC), rectal cancer (RC) tissues, as well as normal tissues." (PMID 41020376, 2025). "Sixty‐six patients with colon cancer, aged 27–80 (57.96 ± 13.79) years, with plasma SIRT1 expression of (3.29 ± 1.43) ng/mL, consist of 39 males and 27 females." (PMID 41020376, 2025). "In conclusion, ZMIZ1 significantly promoted the malignant proliferation of colon cancer cells, possibly by acting as an E3 ubiquitin ligase that regulates the SIRT1/FOXO3a axis, thereby controlling autophagy or apoptosis of colon cancer cells." (PMID 38214831, 2024). "Intestine-specific Sirt1 heterozygous mice have enhanced intestinal tumor formation, whereas intestine-specific Sirt1 pure knockout mice have reduced colon cancer development." (PMID 38214831, 2024). "Curcumin has also been shown to inhibit the activity and expression of SIRT1 and reduce the invasiveness of colon cancer cells." (PMID 38539819, 2024). "Pharmacological inhibition or genetic knockdown of SIRT1 significantly reduced the colony-forming ability of colon cancer cells." (PMID 38539819, 2024). "Aspirin increases SIRT1 expression, promoting cellular senescence in colon cancer cells and exerting anti-tumor activity." (PMID 39598398, 2024).
colon carcinoma (continued). "Collectively, our results suggest that essential oils isolated from Calocedrus formosana act as a promising anticancer agent against colon cancer cells by targeting SIRT1 to induce ROS-mediated autophagy and apoptosis." (PMID 38539819, 2024). "In vitro deacetylation assays performed on SIRT1 immunoprecipitated from SIRT1-positive patient samples confirmed a common decrease of SIRT1 activity in colon tumor tissue." (PMID 37530744, 2023). "Human colon cancers that had been treated with many types of chemotherapy exhibited a SIRT1-dependent oxphos increase." (PMID 37779896, 2023). "Our findings indicate that propofol inhibits SIRT1 in cancer and is advantageous in colon cancer surgical treatment of patients with high SIRT1 expression." (PMID 37490168, 2023). "In conclusion, we demonstrated that propofol inhibits the stemness and EMT of colon cancer cells by downregulating the SIRT1 and the Wnt/β-catenin and AKT/mTOR signaling pathways." (PMID 37490168, 2023). "Curcumin causes ubiquitination of malignant SIRT1 and consequent proteasomal disintegration to suppress the expression of malignant SIRT1 protein, decreasing the malignancy of human colon cancer cells by irreversibly altering the cysteine 67 motif of SIRT1." (PMID 37110167, 2023). "Knock down of SIRT1 in combination with 5-FU in colon cancer xenografts reduced oxphos and increased sensitivity to chemotherapy." (PMID 37779896, 2023). "Experimental research has revealed that SIRT1 is overexpressed in colon cancer cells compared to normal cells." (PMID 37630770, 2023). "Curcumin application has been shown to decrease the expression of SIRT1 protein in colon cancer cells and promote the proteasomal degradation of oncogenic SIRT1." (PMID 37630770, 2023). "Here, we report that both SIRT1 and P‐SIRT1Ser27 are upregulated in colon cancer patients and cell lines." (PMID 34826187, 2022). "In previous studies, we observed a similar protein expression pattern for SIRT1 and PGC1α in a metastatic colon cancer cell line." (PMID 35205159, 2022). "Curcumin treatment reduced the expression of SIRT1 protein in colon cancer cells and facilitated the proteasomal degradation of oncogenic SIRT1." (PMID 35807694, 2022). "Chemoresistance in SIRT1-overexpressing tumors causes cancer cell hyperproliferation and survival, and SIRT1 contributes to colon cancer initiation, invasion, and metastasis." (PMID 35054489, 2022). "Our data show that AntiGan reduces SIRT1 mRNA levels, suggesting that it acts as an epinutraceutical against liver and colon tumor." (PMID 35054489, 2022). "In colon cancer, the administration of resveratrol increases SIRT1 expression and decreases NF-κB, with antiproliferative effects on colon cancer cell lines." (PMID 36235389, 2022). "In the present study, we found that both SIRT1 and SIRT1 phosphorylated on serine 27 were coordinately upregulated in colon cancer patients’ tissues and human colon cancer cell lines." (PMID 34826187, 2022). "In this context, our study proposes a unique collaborative relationship between SIRT1 and Snail in the colon cancer growth and progression." (PMID 34826187, 2022). "SW480 cells display a relatively lower level of endogenous SIRT1, compared to other colon cancer cells examined." (PMID 34826187, 2022). "Both P‐SIRT1Ser27 and total SIRT1 levels were highly elevated in three out of four human colon cancer cell lines relative to normal colon epithelial (CCD841CoN) cells." (PMID 34826187, 2022).
colon carcinoma (continued). "In colon cancer, upregulation of SIRT1 reduced cancer cells proliferation through the ability of SIRT1 to deacetylate β-catenin and promote cytoplasmic localization of the nuclear-localized oncogenic form of β-catenin." (PMID 35326523, 2022). "Other studies indicated curcumin suppressed oncogenicity of human colon cancer cells, through covalent modification of SIRT1 at the cysteine 67 residue and the proteasomal degradation of oncogenic SIRT1." (PMID 33713277, 2021). "For example, SIRT1 has been shown to be significantly up-regulated in acute myeloid lymphoma, prostate and colon cancer, but down-regulated in glioma and gastric cancer." (PMID 34907162, 2021). "In colon cancers, observations that SIRT1 can act as a tumor suppressor have been reported in some studies." (PMID 32636443, 2020). "Oxaliplatin and fluorouracil (5-FU) treatment of colon cancer cells increase OXPHOS through sirtuin 1 (SIRT1) and PGC1-α induction." (PMID 32674438, 2020). "This tumor suppressor activity has been confirmed in vivo after Sirt1 overexpression in a mouse model of colon cancer." (PMID 30304806, 2018). "In colon cancer, Sirt1 suppresses cancer development via a feedback loop, in which c-Myc is involved." (PMID 30304806, 2018). "As regards the two SIRT1 variants investigated, i.e. rs10997870 and rs12778366, rs12778366 female homozygous minor allele carriers had decreased CRC and colon cancer risks as compared to homozygous major allele carriers." (PMID 30410074, 2018). "When SIRT1-Flag tagged expression plasmid was transfected into Human colon cancer HCT116 cell line, the acetylation levels of SMARCA5, MTA2, HMGA1, EGFR, CHD4 and GOT2 decreased as equal amounts of the proteins were immunoprecipitated." (PMID 28676654, 2017). "More than 16 miRNAs modulate SIRT1 expression, among them miR-34a induces colon cancer apoptosis and promotes senescence in endothelial cells via the down-regulation of SIRT1 expression." (PMID 29354057, 2017). "Ectopic overexpression of SIRT1 also greatly reduces proliferation of a human colon cancer cell line, with growth driven by active β-catenin." (PMID 27793039, 2016). "Enterocyte-specific inactivation of SIRT1 reduces the overall intestinal tumor load in the APC+/min mouse model for colon cancer." (PMID 26882112, 2016). "SIRT1 overexpression is sufficient to suppress colon cancer growth, but SIRT1 is positively correlated with malignancy in other types of cancers." (PMID 26824501, 2016). "Despite it has been described that induction of SIRT1 by caloric restriction reduces cell proliferation and tumor formation in a mouse model of colon cancer, SIRT1 abundance is increased in various types of tumors." (PMID 26885609, 2016). "In vitro experiments have demonstrated that ectopic expression of miR-34a into human colon cancer cell lines induced apoptosis, senescence and inhibited migration and invasion by targeting E2F, SIRT1 and Fra-1." (PMID 25894979, 2015). "SIRT1 overexpression in ApcMin/+ mice induces beta-catenin deacetylation, reducing colon tumor formation." (PMID 26318035, 2015).
colon carcinoma (continued). "In support of this theory, Sirt1 overexpression in ApcMin/+ mice induces beta-catenin deacetylation, reducing colon tumor formation; in addition, both genetic and drug-induced Sirt1 activation inhibit growth and/or induce apoptosis in certain cancer models." (PMID 21307403, 2011). "Furthermore, Sirt1 inhibition causes re-expression of the E-cadherin gene (in breast and colon cancer cell lines), whose protein product complexes with β-catenin, and this gene reactivation collectively may suppress the constitutive activation of the WNT signaling pathway." (PMID 21549004, 2011). "Paradoxically, SIRT1 expression is reduced in human colon cancer tissues in general, but significantly over-expressed in human colon cancer tissues associated with microsatellite instability and CpG island methylator phenotype." (PMID 21698133, 2011). "We observed that SIRT1 expression in the normal intestine occurs specifically in the enterocytes, the precursor cells that undergo neoplastic transformation in colon cancers and that SIRT1 is upregulated in rodent intestines in response to CR." (PMID 18414679, 2008). "We show that overexpression of SIRT1 reduces proliferation in colon cancer cell lines and that overexpressing SIRT1 in the enterocytes of APCmin/+ animals mimics the tumor suppressive effects of CR on this colon cancer model." (PMID 18414679, 2008). "We report here that SIRT1 suppresses intestinal tumorigenesis in the APCmin/+ mouse model and inhibits colon cancer growth." (PMID 18414679, 2008). "To analyze the clinical relevance of our findings, we analyzed SIRT1 and β-catenin subcellular expression in a tissue microarray containing 81 human colon cancer samples." (PMID 18414679, 2008). "Suppression of SIRT1 in the DLD1 colon cancer cells increased the amount of nuclear β−catenin while overexpression of SIRT1 in the same cell line led to a dramatic reduction in the nuclear β-catenin pool." (PMID 18414679, 2008). "Here we describe a physiologically relevant tumor suppressive role for SIRT1 in colon cancer formation and growth." (PMID 18414679, 2008). "Together, our data sheds light on the ability of SIRT1 to inhibit β-catenin activity and provides mechanistic insight into the anti-tumorigenic effects of SIRT1 in a well characterized colon cancer model." (PMID 18414679, 2008). "Consistent with this, a significant inverse correlation was found between the presence of nuclear SIRT1 and the oncogenic form of β−catenin in 81 human colon tumor specimens analyzed." (PMID 18414679, 2008). "We find that SIRT1 overexpression inhibits the growth of colon cancer cells dependent on β-catenin activity, suppresses the localization of β-catenin to the nucleus, and significantly attenuates its ability to activate transcription." (PMID 18414679, 2008). "To further explore this possibility, we overexpressed SIRT1 and a catalytically inactive SIRT1 mutant (SIRT1ΔHY) in different human colon cancer cell lines whose growth is driven by constitutively active β-catenin (HCT116 and DLD1)." (PMID 18414679, 2008). "Both breast and colon cancer cell lines were chosen for our study, and several RNAi sequences targeting SIRT1 specifically were tested for their efficacy." (PMID 16596166, 2006). "First, we tested for the possible impact of the re-expression of these genes in colon cancer cells by examining key parameters of the Wnt signaling pathway following SIRT1 inhibition." (PMID 16596166, 2006). "The quantities of SIRT1 in the plasma of patients diagnosed with colon cancer exhibited a noteworthy distinction between the low and moderately differentiated groups, as well as the highly differentiated group [(2.48 ± 1.14) ng/mL vs. (3.69 ± 1.40) ng/mL, p < 0.01]." (PMID 41020376, 2025).
colon carcinoma (continued). "In contrast, low SIRT1 expression in colon cancer was significantly related to differentiation, TNM stage, and distant metastasis (p < 0.05), while in rectal cancer, reduced SIRT1 expression was associated not only with differentiation and TNM stage but also with lymph node metastasis (p < 0.05)." (PMID 41020376, 2025). "The plasma level of SIRT1 in colon cancer patients showed a negative association with CEA (r = −0.251, p = 0.042) and CA199 (r = −0.342, p = 0.005)." (PMID 41020376, 2025). "Similarly, miR-141-3p acts as an oncogene in colon cancer by targeting and inhibiting Sirt1, a tumour suppressor." (PMID 40407536, 2025). "Correlation between serum SIRT1 and tumor markers in patients with colon cancer." (PMID 41020376, 2025). "Here we unveil that 1,25(OH)2D3-bound VDR activates Silent Information Regulator of Transcription, sirtuin 1 (SIRT1), leading to β-catenin deacetylation and nuclear exclusion, downregulation of its pro-tumourigenic target genes and inhibition of human colon carcinoma cell proliferation." (PMID 39494323, 2024). "Although the role of SIRT1 in colon cancer remains controversial." (PMID 38214831, 2024). "We further provide evidence to support the idea that CF-EO-targeted SIRT1 inhibition may be a promising strategy in colon cancer management." (PMID 38539819, 2024). "In colon cancer and melanoma cells, deacetylation by SIRT1 promotes tumor suppressor activity by enhancing the ability of histidine triad nucleotide-binding protein 1 (HINT1) to bind to β-catenin or MITF, resulting in an increase in the tumor suppressor function of HINT1123." (PMID 39479446, 2024). "After subsequent rescue experiments, we also demonstrated that ZMIZ1 could promote the malignant proliferation of colon cancer by facilitating the degradation of SIRT1." (PMID 38214831, 2024). "SIRT1 is a NAD+-dependent deacetylase that has been implicated in the occurrence and progression of various cancers, including gastric cancer, breast cancer, colon cancer, prostate cancers, and some certain hematopoietic malignancies." (PMID 39598398, 2024). "Therefore, we examined the impact of CF-EOs on SIRT1 activity and protein expression in colon cancer cells." (PMID 38539819, 2024). "It was found that The H19/miR-194-5p axis regulates the SIRT1-dependent autophagy pathway, which may impact 5-Fu chemoresistance in colon cancer cells." (PMID 39830506, 2024). "We hypothesized that ZMIZ1 may control the fate of colon cancer cells through the SIRT1/FOXO3a axis." (PMID 38214831, 2024). "In addition, some studies have found that the activation of Notch1/Hes1 signaling pathway, as a downstream pathway of SIRT1, can induce apoptosis in esophageal squamous cell carcinoma and colon cancer cells, as well as inhibit their lymph node metastasis." (PMID 38828455, 2024). "Here, we reveal that 1α,25-dihydroxyvitamin D3 (1,25(OH)2D3, calcitriol), the active metabolite of vitamin D (VD), promotes SIRT1 activation through auto-deacetylation in human colon carcinoma cells, and identify lysine 610 as an essential driver of SIRT1 activity." (PMID 37530744, 2023). "For colon cancer patients who express high levels of SIRT1, propofol may be better than other anesthetics." (PMID 37490168, 2023). "Overall, propofol may be beneficial in patients undergoing colon cancer resection, who express high level of SIRT1." (PMID 37490168, 2023). "Immunohistochemical analysis of human colon tumor tissue microarrays (TMAs) from the Biobank of Hospital Clínico San Carlos (HCSC, Madrid) revealed a significant (p=0.017) positive association between the levels of VDR and SIRT1 proteins." (PMID 37530744, 2023). "The results indicate that propofol may be beneficial in patients with high SIRT1 expression undergoing colon cancer resection." (PMID 37490168, 2023).